RHOA (ras homolog family member A)
Diseases named in the same sentence as RHOA in open-access papers (continued):
Sharing a sentence is not in itself a finding about the gene and the disease.
cancer (continued). "Besides, in a recent research, RhoA was found as a downstream target of WIPF1, an oncogene in many cancers." (PMID 34245091, 2021). "PYK2 via binding to Rab22a-NeoF1 fusion protein is also enriched in exosomes, and the exosomal PYK2 induces RhoA activation in its recipient cancer cells negative for Rab22a-NeoF1 to promote migration, invasion, and lung metastases of these cancer cells." (PMID 33568623, 2021). "The exosomal Rab22a-NeoF1 fusion protein functions in its negative recipient cells, such as activation of RhoA and Stat3 in cancer cells and macrophages, respectively, which is dependent on its binding partner PYK2 from its positive donor cells." (PMID 33568623, 2021). "Similar to the pan-cancer activity demonstrated by a combination of SI-12 with the DNMT inhibitor SGI1027, combining SI-12 with the RhoA inhibitor CCG1423 also resulted in potent anti-cancer activity in PANC-1 and LNCaP cells in addition to that seen in MCF-7 cells." (PMID 33767353, 2021). "Conversely, in cells expressing E7 mutant isoforms, increased RhoA GTP could repress Rac1 activity, promoting an amoeboid-like movement of cancer cells." (PMID 33477952, 2021). "RhoA and RhoC induce multiple signaling pathways, including the PI3K/Akt pathway, mitogen-activated protein kinase kinase 1/2 (MEK1/2)/ERK1/2 pathway, and ROCK pathway in various cancer cells." (PMID 33406809, 2021). "Furthermore, our screen in MCF-7 cells was useful for the discovery of pan-cancer potent combinations, as demonstrated by combinations of SI-12 with either DNMT or RhoA in PANC-1, LNCaP, and MDAMB-231 cancer cell models." (PMID 33767353, 2021). "Besides, we also found RhoA was a downstream target of WIPF1, which was also observed in a previous research in cancer." (PMID 34245091, 2021). "Moreover, using PPI networks, key cancer regulators such as MYC, VEGFA, AKT1, CDKN1A, RHOA, and PTEN are identified." (PMID 33281862, 2020). "NSC23766, a Rac-specific inhibitor that does not affect Cdc42 or RhoA, has shown remarkable antitumor effects in multiple cancers 23-25." (PMID 32206120, 2020). "While we assessed the expression of several well-known molecules implicated in cancer cell migration including P-ERK, RhoA, and Rac1, none of them were affected upon ITGB1 and SLUG knockdown in our CTC model." (PMID 32630254, 2020). "This indicates that although RhoA regulates the migration and invasion of cancer cells, which lead to distant metastasis, it does not significantly affect recurrence." (PMID 31976530, 2020). "PDCD10 inhibits RhoA/ROCK signaling, thus promoting cancer cell survival and metastasis." (PMID 32226386, 2020). "For other genes that are not included in the Sanger database, we also confirm their important role in cancer-related biological processes through literature verification, such as ETS1 and RHOA in hallmark “Activating Invasion and Metastasis”." (PMID 32117445, 2020). "Studies show that RhoA-ROCK signaling and consequent modulation of the cytoskeleton in cancer cells may be involved in regulating cell migration and metastasis." (PMID 33327966, 2020). "The expression of the Rho GTPases RAC1, RHOA, and CDC42 is also altered in several cancer types." (PMID 32526908, 2020). "RhoA can exhibit a crucial role in cancers and ROCK is an effector protein of RhoA." (PMID 33552977, 2020). "The inhibitory effects of RGS proteins on PAR4-mediated downstream signaling and cancer progression were additionally investigated by using several assays including ERK phosphorylation, calcium mobilization, RhoA activity, cancer cell proliferation, and related gene expression." (PMID 32517689, 2020). "In contrast, in the RhoA-negative stage III cancer patients, 1 (6.7%) of 15 patients developed PALN recurrence." (PMID 31976530, 2020). "Studies have shown that RhoA signaling and the PI3K/AKT pathway mediate cancer cell invasion, and the FAK–RhoA pathway may influence cancer cell motility." (PMID 31783709, 2019).
cancer (continued). "Gene expression analysis revealed that its mechanism of action might be attributed, in part, to downregulation of cancer-related genes, such as AKT1, BCL2L1, CCND1, CDK4, PLK1, and RHOA." (PMID 31527550, 2019). "In the present study, we detected more cancer cells in the SLNs but not in the contralateral lymph nodes of RhoA knockdown mice compared to the control group." (PMID 31705019, 2019). "More complete understanding of how SHROOM and RhoA–ROCK pathway coordinately and specifically regulate cancer cell metastasis may throw light on the therapeutic approaches for advanced NPC." (PMID 30683844, 2019). "In our model, this modulation of cancer cell invasiveness is not mediated by RhoA-dependent contractile forces of CAFs." (PMID 29535813, 2018). "Although these data cannot tell us precisely whether VASP modulates YAP1/TAZ at downstream or upstream of RhoA, the data are of clinical significance given the high relevance of the GPCR-RhoA-YAP1/TAZ signaling cascade in cancer progression and metastasis." (PMID 29872721, 2018). "Consequently, CLOCK and BMAL1 control the expression of the components of the RHOA-ROCK-CFL pathway, which alters the dynamics of F-actin/G-actin turnover and promotes cancer cell proliferation, migration, and invasion." (PMID 30287810, 2018). "In RhoA-silenced cancer cell spheroids, CAFs did not increase invasion, confirming the role of RhoA-activation in promoting CAF-induced invasion." (PMID 29535813, 2018). "Consistent with previous reports about MerTK in other malignant tumors, MerTK inhibition by either shRNA or treatment with UNC2250 attenuated invasion and migration in MCL cells, accompanied by decrease in phosphorylated FAK and total RhoA." (PMID 29554921, 2018). "For example, although these three Rho members similarly interact with Rho effectors thus far identified, RhoA, RhoB, and RhoC act on different effectors, namely ROCKi/2, integrins and formin FMNL3, respectively, and exert different functions in cancer cell migration and morphogenesis." (PMID 29749605, 2018). "Furthermore, ephrinB1 depletion by siRNA suppresses EphB2-Fc-induced RhoA activation, and reduces motility and invasiveness of the SW480 and Hs578T human cancer cell lines." (PMID 29059157, 2018). "We found that the crosstalk between CAFs and cancer cells promotes invasion by stimulating the scattering of MDA-MB-231 cells, which was dependent on RhoA/ROCK/phospho MLC signaling in cancer cells but independent of RhoA in CAFs." (PMID 29535813, 2018). "This transmembrane glycoprotein also promotes cancer cell migration and invasion, since the podoplanin cytoplasmic tail interacts with ezrin and/or moesin, members of the ERM protein family, to activate RhoA and promote epithelial-mesenchymal transition (EMT)." (PMID 28938000, 2017). "We demonstrate here, for the first time, that Thrombin, which we found over-represented in SW620Exos, can induce elongated non-aggressive cancer cells to acquire an amoeboid morphology through the involvement of the RhoA/ROCK pathway." (PMID 28680152, 2017). "In cancer cells, the promotion of RCP-dependent α5β1/EGFR1 co-trafficking and signalling increases the invasive migration within FN-rich ECM hydrogels by mediating a Rac to RhoA switch at the leading edge to promote filopodial actin spike protrusions." (PMID 27138333, 2016). "Hence, our results indicate that improper regulation of RhoA/ROCK signaling leading to cytoskeletal rearrangement plays an important role in regulation of growth and polarity in cancer cells in 3D." (PMID 27203208, 2016). "Furthermore, we demonstrated that RhoA inactivation by gene silencing and RhoA inhibition (CCG-1423) suppressed both the cellular proliferative activity and motility of the cancer cells." (PMID 27145964, 2016).
cancer (continued). "Although these data suggest the existence of a “cross talk” between RhoA and DNA repair pathways, the effect of RhoA activity modulation on the sensitivity of cancer cells to radiotherapy has not been examined to date." (PMID 26649141, 2016). "Although RhoA GTPase overexpression/hyperactivation is observed in many malignancies, the effect of RhoA activity modulation on cancer radiosensitivity has not been previously investigated." (PMID 26649141, 2016). "Our finding that reduced migration velocity and invasive activity upon knockdown of Swiprosin-1 is rescued by RhoA-DN (G14VRhoA) supports a negative function of RhoA in cancer cell movement and invasion." (PMID 26079945, 2015). "Taken together, these data suggest that the RhoA-ROCK pathway is involved in mediating the negative regulation of NF-κB by cell–cell contact and that this link may be broken in some cancer cells." (PMID 26148352, 2015). "It not only promotes EMT of cancer cells through activation of SNAIL and HMGA2, but also facilitates the invasion and migration of cancer cells via directly activating transcription of a bunch of invasion or migration-promoting factors, such as LGALS1, OPN and RhoA." (PMID 26123544, 2015). "In less strongly adherent cells, such as macrophages, neutrophils, and cancer cell lines, RhoA activation does not affect cell adhesion but is required for cell migration by inducing cell body contraction." (PMID 24551161, 2014). "Since Sema4D is expressed in T-cells and certain types of cancer cells, Plexin-B1-mediated and IKK-complex-dependent RhoA activation might contribute to reduced bone formation under these circumstances." (PMID 25137062, 2014). "Our findings are in keeping with previous reports showing the importance of RhoA, Rac1 and Cdc42 in cancer progression, and also the crosstalk between these GTPases and other signaling pathways like Src-FAK in the migratory phenotype of cancer cells." (PMID 23799130, 2013). "Berberine also showed anti-metastatic properties in several cancer cell lines, acting on 72 kDa type IV collagenase (MMP2), Cdc42 effector protein 1 (CDC42EP1), and ras-related C3 botulinum toxin substrate 1 (RAC1), transforming protein RhoA (RHOA) and urokinase-plasminogen activator A (PLAU)." (PMID 23213296, 2012). "p120ctn has been shown to stimulate Rac and/or Cdc42 activity and/or inhibit RhoA activity in cells lacking E-cadherin, including fibroblasts and cancer cell lines." (PMID 20668551, 2010). "In fact, studies have demonstrated that RhoA/ROCKactivation can facilitate the spread and invasion of tumors, while theblockade of ROCK can enhance the activation of dendritic cells and T cells,suppress tumor growth, promote cancer cell phagocytosis, and induce anti-cancerimmunity." (PMID 40160560, 2025). "In response to external stimuli, RHOA specifically recruits effector proteins, including ROCK, MLC, LIMK, and cofilin, to initiate downstream signaling, which is essential for actin reorganization, cell motility, cell migration, and metastasis in various cancer types." (PMID 41291745, 2025). "ARHGAP5 can also promote cancer progression regardless of the activation state of RhoA." (PMID 38783033, 2024). "Understanding the consequences of Bcl6 cross-talk with RhoA/MKL/SRF in the brain and other organs during development and adulthood could be key to developing effective treatments for complex diseases such as developmental disorders and cancer." (PMID 37967194, 2023). "Furthermore, DLC1 could induce apoptosis, senescence and autophagy of cancer cells by regulating the EGFR/Akt/ NF-κB signalling pathway, and suppress the proliferation and migration of tumors by modulating DLC1/RhoA pathway." (PMID 37737712, 2023). "Notably, RhoA expression and its impact on prognosis are comparable in NSCLC and other cancers." (PMID 36207695, 2022). "Additionally, G-Rh1 suppressed the mRNA expression of RhoA, ROCK1, MMP1, and MMP9 in cancer cell." (PMID 36500403, 2022).
cancer (continued). "Proteomics studies of various cancer cell types indicated several factors and pathways involved in cell adhesion and MCS formation, such as MAPK, and PAM, Wnt, VEGF, MAPK, and PAM signaling, and factors like among others NFκB, TGF-β, FAK/RhoA/Rock or β-catenin." (PMID 35328492, 2022). "In fact, gene up-regulations are rampant in different cell phenotypes such as in cancer pathologies, an example being the up-regulation of flap endonuclease 1 (FEN1) in cancer progression and up-regulation of the small GTP-binding protein, RhoA, in vascular hypertension." (PMID 33971820, 2021). "Therefore, up-regulation of the actin cytoskeleton/RhoA regulation pathway may increase platinum drug sensitivity and improve prognosis by inhibiting EMT, reducing metastasis and regulating the number of cancer stem cells." (PMID 35087829, 2021). "At present, it is not clear whether the pro-metastatic effect of RhoA is RhoA-effector or cancer type specific." (PMID 31705019, 2019). "Constitutive active RHOA (G14V) and RAC1 (G12V) mutants were described to have transforming properties in fibroblasts, although weakly than RAS oncogenes and for long time they were related to cancer only through their cooperative role in RAS or other oncogene-mediated transformation." (PMID 31248017, 2019). "Given that Ran and RhoA colocalized to the PM/ruffles of TOV-112D cells and Ran forms a complex with RhoA, we reasoned that Ran could recruit RhoA to the PM/ruffles, allowing spatially restricted activation of RhoA signaling in migrating cancer cells." (PMID 31209254, 2019). "While the mechanism of activation of CDC42/RAC1 by RHOG, the MAPK by RAC1, as well as the intersection with the RHOA/ROCK1/2 pathways remain topics for future work, we believe this study sheds the light on RHOG as a potentially promising target for anti-angiogenesis in cancer therapeutics." (PMID 30781697, 2019). "While the importance of non-canonical HH/Gi/RHOA signalling in cancer can only be speculative at the moment, there are evidences to suggest an important role." (PMID 30148884, 2018). "The modes of action of dominant-negative mutants of RhoA in cancers are not clear, but as there is an inverse relationship between RhoA signaling and Rac1 signaling, at least in some cell types it is possible that inhibition of the Rho-regulated pathway results in increased Rac1 signaling." (PMID 30544828, 2018). "What we could suggest from cancer cell migration studies is that in the presence of the BDNF, p75NTR may be activated by TrkB and Kidins220 upon ephrin receptor phosphorylation leading to STAT3 activation and RhoA inhibition." (PMID 30190671, 2018). "Although CASZ1 was reported to modulate EGFL7/RhoA pathway and pRb activity in different cell types, however, given the context-dependent function of CASZ1 in various cancers, we speculated that CASZ1 may have a different mechanism to counteract HCC growth and metastasis." (PMID 29506567, 2018). "Similarly, higher expression of RhoA, ROCK1 and ROCK2 has been found in other types of cancer." (PMID 27203208, 2016). "Moreover, this suggests that a simple Rac to RhoA switch does not accurately describe the dynamics of RhoGTPase activity in invading cancer cells." (PMID 27138333, 2016). "This synthetic compound reduced cancer cell migration and proliferation and succeeded in increasing the survival of xenograft mouse models of prostate cancer by targeting Rac1 and Cdc42 but not RhoA." (PMID 27104658, 2016). "Our results, using stable HeLa cell lines expressing either a constitutively active RhoA (RhoA-V14) or a dominant negative version of this protein (RhoA-N19), suggest that RhoA GTPase activity also regulates cancer cell sensitivity to γ-radiation, by affecting basic DNA repair mechanisms." (PMID 26649141, 2016).
cancer (continued). "Moreover, MAPKs and RhoA/ROCK signalling pathways were found to be deregulated in various cancers and several studies suggest the use of inhibitors of these pathways to counteract cancer cell growth and metastatic development." (PMID 26784247, 2016). "Indeed, an examination of human cancer cell lines treated with RhoA-specific siRNA or the Rho inhibitor Rhosin shows that they are dependent on RhoA function for proliferation and progression (data not shown)." (PMID 26030593, 2015). "Notably, RhoA is a key component of the RhoA/Rock pathway, a well-characterized regulator of cytoskeletal organization and a positive regulator of EMT and the motility, invasion and metastasis of cancer cells, including HCC cells." (PMID 24992599, 2014). "In addition, ROCK, but not RhoA, played a crucial role in the development and progression of cancer VM formation in vitro in MHCC97H cell line." (PMID 25238232, 2014). "In contrast, active RhoA was not affected by TGF-β1 or Ki26894 in non-scirrhous cancer cell lines." (PMID 20145621, 2010). "Another, not incompatible hypothesis is that metastasis of cancers may be affected by RHOA role in cell motility and process formation." (PMID 20236512, 2010). "Since the small GTPases of Ras and Rho families have to be prenylated to play an essential role in carcinoma cell invasion, we attempted to assess if the anti-invasive action of ZOL could be related to Ras and/or RhoA inactivation, following the decreased formation of FPP and GGPP, respectively." (PMID 12771933, 2003). "Consequently, the research on therelationship between MLK3 and the RhoA/ROCK signaling pathway is vital to ourunderstanding of the regulatory mechanisms of cell signaling networks and offersnew targets and strategies for the treatment of HFpEF induced by novel targetedanti-cancer drugs." (PMID 40160560, 2025). "Our findings provide evidence for the role of the hypoxia-inducible NPY/Y5R/RhoA axis in promoting genomic changes and subsequent osseous dissemination in ES, and suggest that targeting this pathway may prevent CIN and disease progression in ES and other cancers rich in NPY and Y5R." (PMID 35484119, 2022). "Hence, also in the context of cancer, it is not clear whether RHOA activation within IECs should be considered as a protective or harmful mechanism." (PMID 33406731, 2021). "Additionally, in contrast to RHOA and RHOC, RHOB localizes not only at the plasma membrane but also on endosomes, multivesicular bodies, and in the nucleus, which could contribute to its contrasting behaviors in cancer biology." (PMID 34771549, 2021). "While the impact of hypomethylation at cg18447419 on the action of AHR-mediated RhoA/Rac1 signaling is unknown, this CpG and SLC9A3 should be considered in future candidate analyses given the known interaction between this pathway and dioxin and its potential role in diseases like cancer." (PMID 33849548, 2021). "Therefore, we suggest that EphA2 and EphA4 can signal via Vav2 and RhoA leading to microtubule destabilisation and subsequently cell–cell repulsion, although we cannot rule out additional signalling events regulating cancer cell repulsion downstream of EphA receptors." (PMID 24795148, 2014). "In addition, as both Cox-2 and CXCR-4 inhibitions are RhoA-independent, further investigations are required to determine whether the invasion of cancer cells without RhoA activation could be reduced by ZOL." (PMID 12771933, 2003). "To confirm the GAP function of StarD13, we performed a pull-down assay to investigate the differences in GTP loading of RhoA and Cdc42 in SKOV-3 and Caov-3 cancer cells in the presence or absence of StarD13." (PMID 34958986, 2022). "Among the assessed mRNAs that were present in cancer-derived EVs and absent in MCF10A-derived EVs, several genes, including SNAIL1/2, TAZ, AXL, RHOA and ROCK1, are well known to promote cell motility." (PMID 33921957, 2021).